CCAR2 (cell cycle and apoptosis regulator 2)
Description:
Core component of the DBIRD complex, a multiprotein complex that acts at the interface between core mRNP particles and RNA polymerase II (RNAPII) and integrates transcript elongation with the regulation of alternative splicing: the DBIRD complex affects local transcript elongation rates and alternative splicing of a large set of exons embedded in (A + T)-rich DNA regions. Inhibits SUV39H1 methyltransferase activity. Mediates ligand-dependent transcriptional activation by nuclear hormone receptors. Plays a critical role in maintaining genomic stability and cellular integrity following UV-induced genotoxic stress. Regulates the circadian expression of the core clock components NR1D1 and BMAL1. Enhances the transcriptional repressor activity of NR1D1 through stabilization of NR1D1 protein levels by preventing its ubiquitination and subsequent degradation. Represses the ligand-dependent transcriptional activation function of ESR2. Acts as a regulator of PCK1 expression and gluconeogenesis by a mechanism that involves, at least in part, both NR1D1 and SIRT1. Negatively regulates the deacetylase activity of HDAC3 and can alter its subcellular localization. Positively regulates the beta-catenin pathway (canonical Wnt signaling pathway) and is required for MCC-mediated repression of the beta-catenin pathway. Represses ligand-dependent transcriptional activation function of NR1H2 and NR1H3 and inhibits the interaction of SIRT1 with NR1H3. Represses the transcriptional activator activity of BRCA1. Inhibits SIRT1 in a CHEK2 and PSEM3-dependent manner and inhibits the activity of CHEK2 in vitro.
Synonyms: DBC-1; DBC1; KIAA1967; NET35; p30 DBC; p30DBC
Tractability: PROTAC: UniProt records ubiquitination sites on it; ubiquitination databases record sites on it; its protein half-life has been measured; a small molecule that binds it is known.
Gene: Protein-coding gene on chromosome 8 (22,604,629 to 22,620,964, forward strand). Ensembl gene ENSG00000158941.
Subcellular location: Nucleus; Cytoplasm; Cytoplasm, cytoskeleton, spindle
Subcellular location (Human Protein Atlas): Nuclear bodies; Nucleoplasm
Pathways (Reactome):
Cellular responses to stimuli: Regulation of HSF1-mediated heat shock response
Gene Ontology:
Molecular function: enzyme binding; enzyme inhibitor activity; protein binding; RNA binding; RNA polymerase II complex binding; adenyl-nucleotide exchange factor activity
Biological process: mitochondrial fragmentation involved in apoptotic process; negative regulation of catalytic activity; negative regulation of cell growth; negative regulation of DNA-templated transcription; negative regulation of intrinsic apoptotic signaling pathway in response to DNA damage; negative regulation of proteasomal ubiquitin-dependent protein catabolic process; positive regulation of apoptotic process; positive regulation of canonical Wnt signaling pathway; positive regulation of DNA damage checkpoint; regulation of DNA-templated transcription; regulation of DNA-templated transcription elongation; regulation of protein deacetylation; regulation of protein stability; regulation of RNA splicing; response to UV; RNA splicing; regulation of circadian rhythm
Cellular component: chromatin; cytoplasm; DBIRD complex; mitochondrial matrix; nuclear body; nucleoplasm; nucleus; spindle
Genetic constraint (gnomAD): Loss-of-function variants: 21 observed, 105.02 expected, observed/expected ratio (o/e) 0.2, 90% interval 0.14 to 0.29. The synonymous counts are far from expectation, so gnomAD's model fits this gene poorly and the ratio says little. Missense variants: 1,126 observed, 1,204.8 expected, observed/expected ratio (o/e) 0.93, 90% interval 0.89 to 0.98. Synonymous variants: 577 observed, 484.44 expected, observed/expected ratio (o/e) 1.19, 90% interval 1.11 to 1.28.
Homologues: Orthologues: chimpanzee CCAR2 (99% identical), macaque CCAR2 (98% identical), guinea pig CCAR2 (93% identical), dog CCAR2 (93% identical), pig CCAR2 (93% identical), mouse Ccar2 (91% identical), rat Ccar2 (91% identical), rabbit CCAR2 (88% identical), zebrafish ccar2 (28% identical), Caenorhabditis elegans ccar-1 (24% identical). Paralogues in human: CCAR1 (35% identical).
Diseases named in the same sentence as CCAR2 in open-access papers:
CCAR2 is named in the same sentence as 37 diseases in open-access papers, as found by Europe PMC text mining. Sharing a sentence is not in itself a finding about the gene and the disease. The quoted sentences say what the papers report.
breast cancer (12 papers, 2013 to 2025). A primary or metastatic malignant neoplasm involving the breast. "CCAR2 deficiency promotes DNA damage-induced apoptosis in breast and non-small cell lung cancer cells and induces cell death in anti-estrogen-resistant breast cancer cells." (PMID 37524873, 2023). "Increasing evidence has shown that CCAR2 upregulation is associated with poor survival among tumor patients with breast carcinoma, gastric carcinoma, esophageal cancer, etc., and CCAR2 may serve as a tumor diagnostic or therapeutic target." (PMID 36239351, 2022). "CCAR2 is required for estrogen-stimulated growth of ERα-positive breast cancer cells as well as estrogen-induced ERα target gene expression." (PMID 37524873, 2023). "TALEN-mediated knockdown of CCAR2 in SW480 colon cancer cells and shRNA-mediated depletion of CCAR2 from MDA-MB-231 breast cancer cells result in low expression of IL-8 compared with that in wild-type cells." (PMID 29416683, 2018). "Deleted in breast cancer 1/cell cycle and apoptosis regulator 2 (DBC1/CCAR2) was named by its deletion at a region 8p22 in breast cancer." (PMID 25823848, 2015). "In addition, CCAR2 stabilizes unliganded ERα and suppresses apoptosis in breast cancer cells." (PMID 37524873, 2023). "For instance, the LIM protein Ajuba plays a crucial role in breast cancer by recruiting deleted in breast cancer-1 (DBC1; also known as CCAR2 or p30DBC) and transcriptional coactivators EP300/CBP to form a tertiary complex." (PMID 38914477, 2024). "Moreover, CCAR2 also functions as a coactivator for the oncogenic TF PEA3/ETV4 and promotes ERα-negative breast cancer cell growth, tumorigenesis, and cancer progression." (PMID 37524873, 2023). "In most cell lines derived from different subtypes of breast cancer or other cancers, DBC1 protein was degraded under hypoxia, suggesting the reduced stability of DBC1 was a general rule in hypoxic conditions, while the mRNA level of CCAR2 was not changed under hypoxia." (PMID 35913115, 2022).
colon cancer (7 papers, 2016 to 2024). "Because BAZ1A is associated with CCAR2 in SFN-treated colon cancer cells, and CCAR2 is part of the DBIRD complex that regulates alternative mRNA splicing, the corresponding molecular targets were examined mechanistically." (PMID 39112459, 2024). "CCAR2 deficiency downregulates expression of mitosis-regulatory genes in squamous cell carcinoma cells and expression of Wnt/β-catenin target genes in colon cancer cells." (PMID 29416683, 2018). "Importantly, CCAR2 is required for tumor growth, metastatic potential, and cancer stem cell-like properties of colon cancer cells, and increased expression of CCAR2 has been associated with poor prognosis and short disease-free survival of CRC patients." (PMID 37524873, 2023). "Recent work by our group showed that CCAR2 plays a critical role in establishing active chromatin landscapes and superenhancers in colon cancer cells by regulating p300- and KMT2D-mediated epigenetic modifications of histone H319." (PMID 37524873, 2023). "Depleting CCAR2 inhibits the growth of tumor xenografts derived from colon cancer and laryngeal squamous cell carcinoma cells." (PMID 29416683, 2018). "In colon cancer cells, SFN treatment increased expression of the DBIRD complex members and demonstrated a requirement for CCAR2 in the BAZ1A splicing mechanism." (PMID 39112459, 2024). "Because CtIP and CCAR2 were previously identified as mechanistic targets for SFN and SFN + JQ1, respectively, we used CRISPR/Cas9 in HCT116 colon cancer cells and observed markedly higher basal ERCC2 expression in CtIP–/– and CCAR2–/– cell lines compared to the parental cell line." (PMID 33809839, 2021). "Another interesting avenue is the synergistic combination of sulforaphane with the BET inhibitor JQ1 in colon cancer models, targeting the non-histone protein Cell cycle and apoptosis regulator 2 (CCAR2) for acetylation and altered Wnt coactivator functionality." (PMID 32938017, 2020).
gastric cancer (3 papers, 2018 to 2022). A primary or metastatic malignant neoplasm involving the stomach. "At the same time, in DEPs detected by iTRAQ technology, we found that cell cycle and apoptosis regulatory protein 2 (CCAR2) decreased after BAG2 knockdown, suggesting that CCAR2 may act as a downstream factor of BAG2 to form miR186-BAG2-CCAR2 axis to regulate gastric cancer cell cycle and apoptosis." (PMID 32082999, 2020).
hepatocellular carcinoma (3 papers, 2018 to 2025). A malignant tumor that arises from hepatocytes. "However, the specific molecular mechanism by which CCAR2 regulates chemosensitization in hepatocellular carcinoma has not been fully elucidated." (PMID 40765823, 2025).
squamous cell carcinoma (3 papers, 2018 to 2022). A carcinoma arising from squamous epithelial cells. "It was reported that in squamous cell cancer, the loss of CCAR2 in mice results in cell cycle progression, suggesting that CCAR2 may function as a tumor suppressor." (PMID 33809336, 2021). "In addition, CCAR2 is required for the expression of a subset of cell cycle-regulated genes in human squamous cell carcinoma cells." (PMID 35672287, 2022).
leukemia (2 papers, 2023 to 2025). A malignant (clonal) hematologic disorder, involving hematopoietic stem cells and characterized by the presence of primitive or atypical myeloid or lymphoid cells in the bone marrow and the blood. "Negative regulation of HDAC3 by CCAR2 was confirmed in a later study showing a role for CCAR2 in the regulation of ELL (eleven-nineteen lysine-rich in leukemia) stability." (PMID 37524873, 2023).
neuroblastoma (2 papers, 2019 to 2024). Neuroblastoma (NB) is the most common solid, extracranial childhood tumor. "Here, we used the R2 platform to examine the association between expression of mRNA encoding CCAR2, Hsp60, and survivin and survival of neuroblastoma patients." (PMID 30609639, 2019). "While the association between survivin and neuroblastoma has been studied, less is known about the role of CCAR2 and Hsp60." (PMID 30609639, 2019). "In addition, although we reported previously that CCAR2 and Hsp60 act cooperatively to increase the survival of neuroblastoma cells, the underlying mechanism is unclear." (PMID 30609639, 2019). "Furthermore, high expression of CCAR2, Hsp60, and survivin was associated with poor survival of neuroblastoma patients." (PMID 30609639, 2019). "Furthermore, expression of mRNA encoding CCAR2 and Hsp60 correlates positively with that of survivin in neuroblastoma tissues." (PMID 30609639, 2019). "Our data demonstrate that high expression of CCAR2, Hsp60, and survivin is predictive of a poor prognosis for human neuroblastoma patients." (PMID 30609639, 2019). "Taken together, the results demonstrate that CCAR2 and Hsp60 act as pro-survival factors in neuroblastoma." (PMID 30609639, 2019). "Next, we examined the correlation between CCAR2, Hsp60, and survivin in 649 and 498 neuroblastoma tissues (data obtained from GEO datasets GSE45547 and GSE62564, respectively)." (PMID 30609639, 2019). "Survivin expression in neuroblastoma tissues and human cancer cell lines correlated positively with expression of CCAR2 and Hsp60." (PMID 30609639, 2019). "Therefore, CCAR2, Hsp60, and survivin are candidate tumor biomarkers and prognostic markers in neuroblastomas." (PMID 30609639, 2019). "We found that CCAR2 interacted with survivin in SH-SH5Y neuroblastoma cells." (PMID 30609639, 2019). "In neuroblastoma, a pediatric tumor, HSP60 is upregulated compared to normal cells; it provides cellular protection by stabilizing survivin via binding with cell cycle and apoptosis regulator 2 (CCAR2) and contributes to the survival of neuroblastoma cells." (PMID 38791521, 2024).
pancreatic cancer (2 papers, 2014 to 2016). "In no doubt, this study warrants further investigation of the role of Sirt1 in pancreatic cancer development as well as of the chemotherapeutic efficacy of Sirt1 inhibitors in preclinical models of human PDAC, guided by the expression of Sirt1 and Ccar2." (PMID 25594010, 2014).
prostate carcinoma (2 papers, 2022 to 2023). A carcinoma that arises from epithelial cells of the prostate gland. "As an AR coactivator, CCAR2 promotes AR transcriptional activity by enhancing its DNA-binding activity and its stability in prostate cancer and osteosarcoma cells." (PMID 37524873, 2023). "In conclusion, lncRNA MIAT participated in prostate cancer by regulating cell proliferation and apoptosis via miR-361-3p/CCAR2 axis." (PMID 36245704, 2022). "In conclusion, we found that lncRNA MIAT knockdown inhibited cell proliferation and induced apoptosis in prostate cancer through miR-361-3p/CCAR2 axis and participated in prostate cancer, which would provide new targets for the treatment of prostate cancer." (PMID 36245704, 2022). "Quantitative real-time PCR assay was performed to detect the mRNA expression of lncRNA MIAT, miR-361-3p, CCAR2, Bax, and Bcl-2 in the prostate cancer tissues or cells." (PMID 36245704, 2022). "Previous studies have found that the expression of miR-361-3p was significantly increased and cell cycle and apoptosis regulator 2 (CCAR2) was decreased in prostate cancer, and miR-361-3p/CCAR2 play critical roles in the regulation of the proliferation and apoptosis of prostate cancer cells." (PMID 36245704, 2022). "Besides, compared with adjacent tissues, the mRNA expression of CCAR2 in prostate cancer tissues was significantly upregulated." (PMID 36245704, 2022). "Similarly, the mRNA expression of CCAR2 in the prostate cancer cell line Du145 cells was significantly increased compared with normal human prostate epithelial cells RWPE-2 cells." (PMID 36245704, 2022). "Similarly, we verified the relationship between miR-361-3p and CCAR2 and confirmed the upregulation of CCAR2 in prostate cancer." (PMID 36245704, 2022). "To assess whether miR-361-3p affected the cell growth of prostate cancer cells by regulating CCAR2, we performed the experiments in Du145 cells after upregulating miR-361-3p and CCAR2." (PMID 36245704, 2022). "Therefore, we assumed that lncRNA MIAT may affect the proliferation and apoptosis of prostate cancer cells by regulating miR-361-3p/CCAR2, and play a certain role in prostate cancer." (PMID 36245704, 2022). "In the study, we investigated the expression of lncRNA MIAT in prostate cancer, and explored whether it can affect the proliferation and apoptosis of prostate cancer cells by regulating the miR-361-3p/CCAR2 axis, so as to provide new targets for the treatment of prostate cancer." (PMID 36245704, 2022).
cervical cancer (1 paper, 2018). A primary or metastatic malignant neoplasm involving the cervix. "Furthermore, CCAR2-regulated IL-8 expression is associated with a shorter survival of cervical cancer patients." (PMID 29416683, 2018). "To better understand its potential role in cancer, we examined gene expression patterns regulated by CCAR2 in cervical cancer cells." (PMID 29416683, 2018). "Next, CCAR2-dependent IL-8 expression was verified in cervical tumor tissues isolated from cervical cancer patients." (PMID 29416683, 2018). "Overall, high IL-8 expression regulated by CCAR2 plays a critical role in aggressive progression of cervical cancer." (PMID 29416683, 2018). "In contrast to previous studies, we found that CCAR2 siRNA-transfected cells show the upregulation of IL-8 in HeLa and SiHa cervical cancer cells following oxidative stress; the reason for this may be that previous studies used different cell types or stimuli." (PMID 29416683, 2018). "The negative correlation between CCAR2 and IL-8 expression was confirmed by examining mRNA and protein levels in tissues from cervical cancer patients." (PMID 29416683, 2018).
glioma (1 paper, 2023). A benign or malignant brain and spinal cord tumor that arises from glial cells (astrocytes, oligodendrocytes, ependymal cells).
liver cancer (1 paper, 2025). An epithelial or non-epithelial malignant neoplasm that arises from the liver. "In vivo, TFPI2 overexpression decreased tumor volume in an orthotopic nude mouse liver cancer model, but CCAR2 knockdown reversed this effect." (PMID 40765823, 2025). "Additionally, immunofluorescence co-localization showed that TFPI2, CCAR2, and BRCC3 had clear co-localization in liver cancer cells." (PMID 40765823, 2025).
liver disease (1 paper, 2025). "As shown in the heat map, male offspring exposed to HSD exhibited differential expression of ten genes associated with liver disease compared to normal offspring: Ager, Dph1, Steap4, Nfe2l1, Ppara, Rbmx, Nr1d1, Ccar2, Axl, and Abcg5." (PMID 41036197, 2025).
lymphoma (1 paper, 2024). A malignant (clonal) proliferation of B- lymphocytes or T- lymphocytes which involves the lymph nodes, bone marrow and/or extranodal sites. "GFI-1, Sin3A, PRMT5 and CCAR2 genes were uniformly expressed at high levels also in SUP-M2 cells, thus confirming their potential relevance in lymphoma." (PMID 39478125, 2024).